ALB (albumin)
Diseases named in the same sentence as ALB in open-access papers (continued):
Sharing a sentence is not in itself a finding about the gene and the disease.
atrial fibrillation (continued). "The results of the MR analysis indicate a significant inverse association between genetically predicted serum albumin concentration (g/L) and the risk of atrial fibrillation (Beta = −0.172, OR = 0.842, 95% CI: 0.753–0.941, p = 0.002)." (PMID 38655495, 2024). "Mortality within 30 days was associated with the presence of atrial fibrillation, higher levels of uric acid, lower values for serum bicarbonate and albumin, and dilated left atrium." (PMID 38672783, 2024). "In view of this, this study aims to deeply analyze the causal relationship between serum albumin and atrial fibrillation." (PMID 38655495, 2024). "Especially in patients with atrial fibrillation who undergo ablation treatment, serum albumin levels can predict the risk of postoperative recurrence, further highlighting its important role in the pathological process of atrial fibrillation." (PMID 38655495, 2024). "Predictors of ICU admission following radical CRC resection include age, preoperative serum albumin level, nutritional risk screening, atrial fibrillation, COPD, FEV1/FVC, and surgical route." (PMID 38965472, 2024). "Our findings showed that a decrease in serum albumin level significantly increases the risk of atrial fibrillation, which is consistent with previous observational studies." (PMID 38655495, 2024). "Subsequently, we also verified the mediating role of serum metabolites in the causal relationship between serum albumin and atrial fibrillation." (PMID 38655495, 2024). "Age, body mass index, atrial fibrillation, New York Heart Association functional class, and albumin were independent predictors of low NT-proBNP levels in HFpEF patients." (PMID 38013260, 2023). "Patients with atrial fibrillation and/or other cardiovascular diseases were shown to have an increased risk of cardio-thromboembolic events when their serum albumin levels were low." (PMID 36739380, 2023). "The reduction in the urinary albumin/creatinine ratio caused by high creatinine levels has also been associated with an increased risk of atrial fibrillation." (PMID 34497820, 2021). "Patients with high albumin level were associated with a decreased risk of atrial fibrillation compared with patients with low serum albumin (OR[odds ratio]: 0.62, 95% CI [0.44, 0.89]; I 2 = 76%; P = 0.009)." (PMID 34490334, 2021). "Model 4 included NT-proBNP, and a higher level of NT-proBNP was associated with higher risk for pump failure death while LVEF, potassium, albumin, and history of atrial fibrillation fell out of the model." (PMID 33301080, 2021). "In the dose-response analysis, for each 10 g/L increase in serum albumin level, the risk of atrial fibrillation decreased by 36% (95% CI: 0.51-0.81, I 2 = 87%, P < 0.001)." (PMID 34490334, 2021). "It is widely reported that low albumin level correlates with an increased risk of cardiovascular diseases and atrial fibrillation (AF)." (PMID 24734185, 2014). "Furthermore, albumin reflects nutritional status, a parameter independently associated with atrial fibrillation recurrence." (PMID 40860368, 2025). "Serum albumin may play another important role in preventing the risk of atrial fibrillation, which is inseparable from its inhibitory effect on inflammation and blocking the process of atherosclerosis." (PMID 38655495, 2024). "Therefore, this study aims to further explore the causal relationship between serum albumin and atrial fibrillation and its potential mechanism." (PMID 38655495, 2024). "Further mediation MR analysis revealed that serum albumin may mediate the causal relationship with atrial fibrillation by affecting two serum metabolites, docosatrienoate and oleate/vaccenate, and the mediating effect was significant." (PMID 38655495, 2024). "The leukocyte to albumin ratio could provide key clues in clinical practice and in thromboembolism risk assessment in the setting of atrial fibrillation." (PMID 36739380, 2023).
atrial fibrillation (continued). "It has been demonstrated throughout this investigation that the leukocyte to albumin ratio could provide key clues in clinical practice and contribute to thromboembolism risk assessment in the setting of atrial fibrillation." (PMID 36739380, 2023). "In conclusion, we found that the left atrial diameter, albumin, the type of Af, whether other arrhythmias were combined, the duration of Af attack time were significantly associated with Af recurrence." (PMID 35155619, 2021). "Our study indicates that low serum albumin can increase the risk of symptomatic or asymptomatic HT after intravenous thrombolytic therapy, and the effect remained significant even after adjusting for age, Atrial fibrillation, and NIHSS." (PMID 28798356, 2017). "This study aimed to assess the association between albumin levels and bleeding risk in atrial fibrillation (AF) patients treated with DOACs." (PMID 40273298, 2025). "The key risk factors included advanced age, atrial fibrillation, NIHSS score, nasogastric tube insertion, mechanical ventilation, and elevated MLR, while higher albumin levels were protective." (PMID 42150599, 2026). "Factors significantly related to recurrence included gender, age, admission NIHSS and BI scores, atrial fibrillation, hyperhomocysteinemia, alcohol use, sedentary lifestyle, albumin, and LDL levels (P < 0.05)." (PMID 40475992, 2025). "Other important features include neutrophil/lymphocyte ratio (10.1%), platelet distribution width (9.7%), large vessel occlusion (8.6%), atrial fibrillation (7.4%), albumin level (5.9%), and intravenous thrombolysis (5.6%)." (PMID 41409215, 2025). "TAVR patients with RASP had a distinct clinical profile, including higher EuroSCORE II, lower BMI, reduced albumin levels, and a greater prevalence of atrial fibrillation and hyperuricemia." (PMID 40714907, 2025). "We found that the presence of atrial fibrillation, urinary albumin/creatinine ratio (UACR) ≥16.5 mg/g Cr, serum levels of adropin<2.1 ng/mL and NT-proBNP ≥19,540 pmol/mL were independent predictors for AKI in patients with ADHF." (PMID 40496057, 2025). "Low albumin levels are a known correlate of severity in many pathologies, including atrial fibrillation." (PMID 41210872, 2025). "The predictors included in the model were: Obstructed blood vessel_5 (basilar artery occlusion), TOAST_2 (cardioembolic stroke), atrial fibrillation, albumin (ALB) levels, NIHSS score, and diastolic blood pressure (DBP)." (PMID 40697574, 2025). "Using data from large-scale genome-wide association studies, we conducted a two-sample Mendelian randomization (MR) analysis and a mediation MR analysis, using serum albumin as the exposure variable and atrial fibrillation as the outcome variable." (PMID 38655495, 2024). "We set serum albumin levels as the exposure factor, atrial fibrillation as the study outcome, and set strict statistical significance thresholds (P < 5e-08)." (PMID 38655495, 2024). "Through multiple long-term and large-scale cohort studies, a significant trend has emerged: a decrease in serum albumin levels is significantly correlated with a relative increase in the incidence of atrial fibrillation." (PMID 38655495, 2024). "This series of causal links deeply reveals the key mediating role of these serum metabolites in the relationship between serum albumin and atrial fibrillation." (PMID 38655495, 2024). "Although several observational studies have linked serum albumin to cardiovascular disease and considered it as an important biomarker, little is known about whether increasing or maintaining serum albumin levels can effectively improve the prognosis of patients with atrial fibrillation." (PMID 38655495, 2024). "The severity of various diseases, including atrial fibrillation, is known to be correlated with low albumin levels." (PMID 36739380, 2023).
atrial fibrillation (continued). "Patients with reduced LVEF were more likely to present with shortness of breath; had a higher proportion of atrial fibrillation/flutter rhythm; and had higher levels of creatinine, hs-cTnI, C-reactive protein, and D-dimer but lower nadir levels of albumin." (PMID 38137638, 2023). "According to the findings of these analyses on the relationship between the leukocyte to albumin ratio and the severity of atrial fibrillation, LAR and increased BNP, DD PROBNP and HSTNI are the variables associated with atrial fibrillation." (PMID 36739380, 2023). "Low albumin and increased leukocyte counts are also known to be very important parameters of atrial fibrillation severity." (PMID 36739380, 2023). "Similarly, albumin, the major protein in the serum, is also considered an acute phase reactant protein that has osmotic and anti-inflammatory properties, and a low albumin level is a known factor associated with severity in many pathologies, including atrial fibrillation." (PMID 36739380, 2023). "Some studies have described that the presence of atrial fibrillation and higher albumin levels were protective against the development of ARN." (PMID 35497792, 2022). "Notable examples include links from blood pressure to atrial fibrillation, serum albumin to lung function, and RBW to cardiovascular disease." (PMID 33441555, 2021). "This study aims to assess the relationship between albumin and atrial fibrillation and the potential dose-response effect." (PMID 34490334, 2021). "Further studies are needed to explore the effect of induction of elevated serum albumin levels on the prevention of atrial fibrillation." (PMID 34490334, 2021). "In univariate analysis for HT, atrial fibrillation and level of albumin were identified as significant factors (P < 0.001, P = 0.001 respectively)." (PMID 28798356, 2017). "Compared with warfarin users, DOAC users had a significantly higher rate of atrial fibrillation, higher levels of hemoglobin and albumin, lower levels of PT-INR and BUN, a lower rate of LDA use, and a higher rate of lower GIB." (PMID 28863196, 2017). "In univariate analysis for HT, atrial fibrillation and level of albumin were identified as significant factors (P < 0.05)." (PMID 28798356, 2017). "For example, we will use indefinite anticoagulation (unless contraindicated) in cases of NS with low albumin levels and a compelling indication for anticoagulation such as atrial fibrillation or multiple VTE." (PMID 24829800, 2014). "This case is relatively straightforward since the patient has many compelling indications for pharmacological anticoagulation, such as atrial fibrillation and an albumin level of 1.7 in a setting of MN." (PMID 24829800, 2014). "The second theoretical case was a 47-year-old female with NS secondary to MN, an albumin level of 1.7 g/l, congestive heart failure, and atrial fibrillation." (PMID 24829800, 2014). "These variables include admission NIHSS score, age, ASPECT score ≥7, neutrophil/lymphocyte ratio, platelet distribution width, large vessel occlusion, atrial fibrillation, albumin level, and intravenous thrombolysis, which were used for subsequent machine learning model construction." (PMID 41409215, 2025). "Although the potential mechanism of serum albumin reducing the risk of atrial fibrillation has not been conclusive, we can explore it from multiple perspectives." (PMID 38655495, 2024). "This indicates that the causal relationship between serum albumin and reduced risk of atrial fibrillation is not dominated by a single or small number of instrumental variables, but is based on comprehensive data analysis and reliable conclusions." (PMID 38655495, 2024). "In multivariable adjusted analyses, only “other cardiac diseases” (a category including cardiac dysrhythmia, atrial fibrillation, tachycardia, pericarditis, cardiac arrest, and transient ischemic attack), PVD, and serum albumin remained statistically significant risk factors associated with frailty." (PMID 37675341, 2023).
atrial fibrillation (continued). "The left atrial diameter, albumin, type of Af, whether other arrhythmias were combined, and the duration of Af attack time were associated with Af recurrence in this sample." (PMID 35155619, 2021). "Compared with the higher HALP score patients, those with a lower HALP score were more likely to be older; be female; have atrial fibrillation; have lower lymphocyte, hemoglobin, and albumin levels; and have higher platelet counts, frequencies of cardioembolic stroke, and baseline NIHSS scores." (PMID 33510706, 2020). "After adjusting for age, sex, BMI, DM, Atrial fibrillation, body fat percentage, E/e’, albumin, eGFR, HDL-cholesterol, BNP, aspirin and SAF, SAF level was found to be a significant independent factor associated with reduced EC (odds ratio 2.10, 95% confidence interval 1.13–4.05; P = 0.02)." (PMID 32326893, 2020). "Furthermore, they had lower troponin T concentrations, higher serum albumin and uric acid levels and more frequent temporary/persistent atrial fibrillation." (PMID 30452453, 2018). "Furthermore, the presence of atrial fibrillation obviates the need to consider serum albumin in this patient." (PMID 24829800, 2014). "Thus far, most of the studies that previously assessed the association between atrial fibrillation and systemic or severe inflammation did not include the leukocyte count and albumin-derived ratios." (PMID 36739380, 2023). "Furthermore, a significant negative linear relationship between serum albumin and the risk of atrial fibrillation (P nonlinearity = 0.33) was found." (PMID 34490334, 2021). "Furthermore, this study not only validates the predictivepower of the BUN/albumin ratio (BAR) but also demonstrates the superiorperformance of a nomogram model that integrates BAR with other prognostic factorsin predicting ICU mortality among patients with atrial fibrillation." (PMID 40776939, 2025). "For instance, higher NIHSS scores, elevated ALB levels, increased DBP, and the presence of atrial fibrillation contribute to a higher total score, indicating an elevated risk of HT." (PMID 40697574, 2025). "The NAFLD fibrosis score (NFS) and the FIB-4 scores, obtained from age, body mass index (BMI), and laboratory parameters such as platelets count, albumin, and transaminases, may predict the new onset of atrial fibrillation (AF) in patients with HFpEF." (PMID 37958649, 2023). "Covariates were enrolled including age, sex, BMI, atrial fibrillation, NYHA functional class, hemoglobin, albumin, sodium, eGFR, and high-sensitivity C-reactive protein." (PMID 38013260, 2023). "In multivariable logistic regression analysis, independent determinants of LT3S were atrial fibrillation, systolic blood pressure, NYHA functional class, hemoglobin, albumin, and blood urea nitrogen." (PMID 34215247, 2021). "Estimated-GFR and atrial fibrillation showed the better relation with NT-proBNP, followed by polypharmacy, CRP, albumin and age." (PMID 27077910, 2016). "Of patients with normal nutrition, those who exhibited frailty were older and more likely to have cognitive impairment, atrial fibrillation, and lower albumin levels than those without frailty." (PMID 39861351, 2025). "Other studies presented the correlation between lower albumin plasma concentration and higher incidence of international normalized ratio of prothrombin time (PT-INR) >3.0 and major bleeding events in patients with atrial fibrillation treated with warfarin." (PMID 40051558, 2025). "The results of the univariate Cox regression analysis indicated that age, atrial fibrillation, hs-CRP, serum albumin, CAR, serum creatinine, eGFR, hemoglobin, lactate dehydrogenase (LDH), log-transformed NT-pro BNP, LVEDD, LVESD, LVEDV, and LVESV were significantly associated with the risk of MACE." (PMID 39629178, 2024). "The results showed a significant negative correlation between serum albumin and atrial fibrillation (Beta = −0.172, OR = 0.842, 95% CI: 0.751–0.943, P = 0.003)." (PMID 38655495, 2024).
atrial fibrillation (continued). "Moreover, they reported LVEF, atrial fibrillation, LDL cholesterol, albumin, and CCR to be significant and independent predictors for mortality in multivariate Cox regression model." (PMID 25147737, 2014). "The neutrophil percentage-to-albumin ratio (NPAR) and other emerging leukocyte counts/albumin ratios have been reliable systemic inflammation-based predictors of mortality and complications in various diseases, but they have not yet been used with atrial fibrillation." (PMID 36739380, 2023).